CALR (calreticulin)
Diseases named in the same sentence as CALR in open-access papers (continued):
Sharing a sentence is not in itself a finding about the gene and the disease.
leukemia (20 papers, 2015 to 2026). A malignant (clonal) hematologic disorder, involving hematopoietic stem cells and characterized by the presence of primitive or atypical myeloid or lymphoid cells in the bone marrow and the blood. "Specifically, a significant increase in circulating CD4+ and CD8+ T lymphocytes was found upon recognition of leukemia-associated antigens (LAA) suggesting ecto-CALR and ICD stimulation as a potential strategy to improve clinical patients’ outcomes in AML." (PMID 38730609, 2024). "The expression of CALR was associated with the metastasis and invasion of bladder cancer, leukemia, and other malignant tumors." (PMID 36579538, 2022). "In the present study, a cohort of 305 Chinese patients with hematopoietic neoplasms was screened for CALR mutations, with the aim of uncovering the frequency of CALR mutations in leukemia and MPNs." (PMID 26377485, 2016). "Therefore, in addition to MPNs, the mutation profile of CALR in other hematopoietic diseases such as leukemia and MDS has been given more attention than in the past." (PMID 26377485, 2016). "Therefore, in the present study, a cohort of 305 Chinese patients with hematopoietic neoplasms was screened for CALR mutations, with the aim of uncovering the frequency of CALR mutations in leukemia and MPNs." (PMID 26377485, 2016). "Intensive treatment for the leukemia allowed for expansion of the original CALR mutated clone." (PMID 26904322, 2016). "However, little is known about CALR mutation in Chinese patients with leukemia." (PMID 26377485, 2016). "There was a higher incidence of leukemia transformation and thrombosis in patients carrying mutant CalR genes in our group." (PMID 40572650, 2025). "DADS-induced differentiation of human leukemia HL-60 cells was found to be related to the decrease in DJ-1 and calreticulin (CRT) contents." (PMID 34745287, 2021). "Driver mutational status did not impact overall and leukemia-free survival; conversely, CALR (type 1/1-like more than type 2/2-like) and MPL mutations were significantly associated with a higher risk of MF progression, as previously reported." (PMID 38238287, 2024). "Indeed, PKBH1 has been shown to induce ICD in T-ALL leukemia cell lines through the expression of CALR on the cell surface and by releasing HSPs as well as HMGB1, shedding light on the therapeutic potential of CD47 agonist peptides in the treatment of ALL." (PMID 38730609, 2024). "Particularly, ICD-related DAMPs, especially CALR and HSPs, may play a crucial role in leukemia by enhancing both innate and adaptive immune responses." (PMID 38730609, 2024). "The results demonstrate that CALR mutation status is an important diagnostic factor in MPN patients without JAK2 mutation while it is negative in leukemia patients." (PMID 26377485, 2016). "Only one of the leukemia patients was found to have a CALR SNP, rs143880510." (PMID 26377485, 2016). "However, all of the leukemia patients had negative results for CALR mutations." (PMID 26377485, 2016). "Within our given follow-up, we did not detect a significant difference in overall survival or leukemia-free survival between JAK2- and CALR-mutated patients." (PMID 41463191, 2025). "With regards to MPN-associated catastrophic events, S100A8High type 1-like CALR-mutated MPN patients were not more likely to suffer from major thrombotic events, secondary MF, or leukemia transformation." (PMID 37240094, 2023). "Calreticulin is expressed on cell surfaces of human leukemias, lymphomas, and solid cancers, but not on non-tumor or normal cell surfaces." (PMID 28484448, 2017).
anemia (19 papers, 2015 to 2025). A reduction in the number of red blood cells, the amount of hemoglobin, and/or the volume of packed red blood cells. "In the 72 CALR-positive patients with delayed (> 2 years) ruxolitinib start, anemia and a reduced ruxolitinib starting dose were associated with poorer overall survival." (PMID 39831987, 2025). "Anagrelide can be considered in patients who are resistant or intolerant to HU, although clinically significant anemia and long-term bone marrow fibrosis, particularly in CALR-mutated cases, have raised concerns." (PMID 41228192, 2025). "In patients with PMF, CALR mutations were associated with a younger age and higher platelet counts and were less likely to be related to anemia and leukocytosis." (PMID 36359414, 2022). "Regarding PMF patients, those that harbor CALR mutation have younger age, higher platelet count and less anemia compared to those JAK2 and MPL mutated." (PMID 35562964, 2022). "Based on their data, they concluded that CALR-mutated patients have favorable prognostic features such as decreased anemia and leukocytosis, while CALR-/ASXL1+ have decreased survival." (PMID 34833034, 2021). "The incidence of anemia as an adverse event was significantly higher in the CALR mutation‐positive group." (PMID 31107982, 2019). "Nevertheless, the combined use of danazol, erythropoiesis-stimulating agents, iron chelation therapy and ruxolitinib dose optimization have been proposed as a means of mitigating the burden of anemia and may be useful in CALR-mutated patients." (PMID 39831987, 2025). "While it may be difficult to find prognostic factors for response in small cohorts, the identification of anemia as a major contributor to worse prognosis also in CALR-mutated patients confirms that anemia should be a key target of MF therapies." (PMID 39831987, 2025). "In addition, shorter survival and anemia were associated with higher CALR VAF in a study including 121 patients with CALR-mutated MF, suggesting a more advanced disease." (PMID 37568719, 2023). "Additionally, our study suggested that a higher CALR mutant burden is associated with advanced disease phenotypes, such as leukocytosis and anemia in all patients with MPN." (PMID 36359414, 2022). "Although Hb levels decreased in a similar manner, the incidence of anemia was significantly higher in the CALR‐ET group than in the JAK2‐ET group, because baseline Hb levels were significantly lower in the CALR‐ET group." (PMID 31107982, 2019). "Regarding treatment‐related adverse events, the number of adverse events (anemia) was significantly higher in the CALR‐ET group (five patients [45.5%]) compared with the number of such events in the JAK2‐ET group (five patients [14.7%]; P = 0.037)." (PMID 31107982, 2019). "However, in transplant-age patients with the CALR mutation, symptoms response was significantly lower (52.5% versus 69.3% in JAK2-mutated patients, p = 0.01) and overall anemia rate was higher (55.4% versus 42.9%, p = 0.05)." (PMID 39831987, 2025). "PMF, one of the most complex and rare malignant tumors in MPNs, is frequently but not always accompanied by JAK2, CALR mutation, aberrant cytokine expression, bone marrow fibrosis and anemia, etc.." (PMID 34633991, 2021). "Notably, the cumulative incidence of anemia was lower in PMF patients harboring the driver CALR mutation versus JAK2- and MPL- mutants; conversely, “triple negative” patients for the three driver mutations manifested the highest cumulative incidence of anemia." (PMID 35045875, 2022).
glioma (19 papers, 2015 to 2024). A benign or malignant brain and spinal cord tumor that arises from glial cells (astrocytes, oligodendrocytes, ependymal cells). "In addition, as the core component of risk score, CALR was proved to mediate the invasion and polarization of macrophages in gliomas." (PMID 35418980, 2022). "In the TCGA, glioma patients with high CALR expression were associated with decreased survival." (PMID 35418980, 2022). "When CALR is over-expressed in glioma cells, there is an increased propensity for radiation-induced apoptosis through the suppression of AKT signaling." (PMID 38786045, 2024). "The NDV infection of glioma cells induced the upregulation of DAMPs, such as calreticulin (Ecto-CRT), heat-shock proteins (HSP), high mobility group box 1 (HMGB1), and ATP." (PMID 35327364, 2022). "Hypoxic or normoxic glioma cell apoptosis and the cell surface exposure of calreticulin (CRT) were detected by flow cytometry." (PMID 36238646, 2022). "Bortezomib’s efficacy for solid tumors is inadequate due to resistance to cell death induction; nevertheless, insertion of arginylated calreticulin into the plasma membrane of glioma cells treated with bortezomib can initiate the apoptotic pathway." (PMID 35004322, 2021). "Treatment of the glioma cells with the ER stress inhibitor 4-phenylbutyric acid (4-PBA) largely abrogated TMZ-induced calreticulin translocation and phagocytosis 19, supporting a critical role of ER stress responses in generating these effects." (PMID 32198351, 2020). "A biomarker panel consisting of AACT, TSP4, MDHM, CALR, LEG1, and AHSG showed the best diagnostic performance for the detection of gliomas, with an area under the curve (AUC) value of 0.958." (PMID 32922940, 2020). "Down-regulation of CALR by antisense was found to increase sensitivity of neuroblastoma × glioma NG-108–15 cells to cytotoxic calcium overload." (PMID 27566066, 2016). "In the TCGA, macrophages were more active in glioma patients with high CALR expression." (PMID 35418980, 2022). "Furthermore, prolonged oxaliplatinum treatment resulted in elevated translocation of calreticulin to the cell surface in glioma cells." (PMID 35046546, 2022). "It has been reported that HSP70 and calreticulin are beneficial for glioma patients, while ATP could serve as a critical signaling molecule supporting glioblastoma growth." (PMID 33614649, 2021). "Additionally, lower CALR levels have been observed in glioma tissues than in normal brain tissues, and CALR expression is correlated with glioma grade and patient survival." (PMID 32922940, 2020). "Interestingly, AACT, LEG1, and AHSG are blood or CSF biomarkers of gliomas, and CALR is correlated with glioma grade and patient survival." (PMID 32922940, 2020). "Using publicly available datasets of scRNA seq of glioblastoma, both CALR and STC1 expression are increased as a function of glioma grade." (PMID 38786045, 2024). "In this review, we examined the role of phagocytic cell death in gliomas and strategies to modulate the balance between “don’t-eat-me” CD47/SIRPα and “eat-me” CALR/STC1 axes for therapeutic benefits." (PMID 38786045, 2024). "Therefore, CALR was hypothesized to play a vital role in the tumor microenvironment of glioma." (PMID 35418980, 2022). "Compared with healthy controls, the abundance of urinary AACT increased in gliomas patients, while the abundance of urinary TSP4, MDHM, CALR, LEG1, and AHSG decreased in gliomas patients." (PMID 32922940, 2020). "After targeted proteomics validation, we identified a biomarker panel (AACT, TSP4, MDHM, CALR, LEG1, and AHSG) with an area under the curve (AUC) value of 0.958 for the detection of gliomas." (PMID 32922940, 2020). "ROC curve analysis showed that the combination of six urinary proteins (AACT, TSP4, MDHM, CALR, LEG1, and AHSG) can effectively discriminate the gliomas patients from healthy controls with the AUC of 0.952." (PMID 32922940, 2020).
glioma (continued). "Glioma cells, upon infection by NDV, revealed the upregulation of calreticulin (Ecto-CRT) and of heat-shock proteins (HSPs)." (PMID 31480379, 2019). "To date, there has not been an analysis of CALR expression in newly diagnosed gliomas relative to post radiation to ascertain if CALR is increased." (PMID 38786045, 2024). "CALR closely interacted with PDIA3 (also known as ERp57) and prolyl 4-hydroxylase β polypeptide (P4HB, also known as PDIA1), which have been reported as prognostic markers in cervical cancer, hepatocellular carcinoma, glioma, and KIRC." (PMID 36338983, 2022). "It was observed that urinary AACT and GELS were significantly upregulated in glioma patients compared to healthy controls, whereas urinary TSP4, MDHM, RINI, CALR, TENA, LEG1, and AHSG were significantly downregulated in glioma patients compared to healthy controls." (PMID 32922940, 2020). "LRP1, the other receptor of CALR on phagocytes, has not been studied in gliomas." (PMID 38786045, 2024). "The top 20 co-expressed neighbors were selected, and the core genes PFN1, CALR, thymosin beta 10 (TMSB10), HLA.A, CD74 (HLADG), HLA.DRA, HLA.B, TUBB, and TUBA1A were found to play pivotal roles in the network, suggesting that immune genes are involved in glioma formation." (PMID 34660294, 2021).
myeloid neoplasm (19 papers, 2016 to 2025). Proliferation of myeloid cells originating from a primitive stem cell. "CALR mutations are an important diagnostic marker in patients with suspected MPN which was recognized by the 2016 revision to the WHO classification of myeloid neoplasms and acute leukemia which included CALR mutations as one of the major criteria for the diagnosis of ET and PMF." (PMID 33806036, 2021). "Here, we observed for the first time a tandem sequence repeats of 18 bases repeating 4.5 times overlapping with the most common MMEJ-del in myeloid malignancy, CALR." (PMID 39607705, 2024). "Mutational analyses of 13 genes commonly mutated in myeloid malignancies, including Janus Kinase 2 (JAK2), calreticulin (CALR), thrombopoietin receptor (MPL), and colony‐stimulating factor 3 receptor (CSF3R) was negative on peripheral blood testing." (PMID 35898175, 2022). "These myeloid malignancies arise due to acquired somatic stem cell lesions affecting calreticulin (CALR), myeloproliferative leukemia virus proto-oncogene (MPL), and the tyrosine kinase Janus kinase 2 (JAK2), usually displaying a valine-to-phenylalanine mutation at 617 (JAK2V617F)." (PMID 36910610, 2023). "In this context, identifying mutations in MPN driver genes (JAK2, CALR, or MPL) or other myeloid neoplasm-associated genes (ASXL1, EZH2, TET2, IDH1, IDH2, SRSF2, and SF3B1) hints to the clonality of hematopoiesis and allows distinction from reactive conditions." (PMID 34830822, 2021). "In this case report and review of 12 additional cases with concurrent CALR-mutation and BCR-ABL1 fusion, we highlighted the importance of integrated clinical, morphologic, and molecular genetic data for classifying atypical myeloid neoplasms for treatment and responses of patients." (PMID 32000382, 2020). "In this case report and review of additional 12 cases with simultaneous presence of CALR-mutation and BCR-ABL1 fusion, we highlighted the importance of integrating clinical, morphological, and molecular genetic data for classifying atypical myeloid neoplasms." (PMID 32000382, 2020). "TET2 mutations have been observed to co-occur with NPM1, FLT3-ITD, JAK2, ASXL1, calreticulin (CALR), SF3B1 and RUNX1 revealing the range of epigenetic connections to cellular processes amongst various myeloid malignancies." (PMID 34065087, 2021). "For example, microhomology-mediated recurrent deletions of CALR, ASXL1, and SRSF2 and non-recurrent deletions in TET2, DNMT3a, CEBPA, and RUNX1 have been reported in myeloid neoplasms." (PMID 36011278, 2022).
pancreatic cancer (19 papers, 2015 to 2026). "Several studies have also implicated CALR in oncogenesis, including esophageal squamous cell carcinoma, gastric cancer, bladder cancer, breast cancer, pancreatic cancer, hepatocellular carcinoma, prostate cancer, ovarian cancer and glioma." (PMID 33221760, 2020). "They observed that high expression of calreticulin was positively associated with tumor stage and metastasis and that calreticulin regulated cell proliferation, migration and invasion of pancreatic cancer cells in a MEK/ERK pathway dependent manner." (PMID 26287160, 2015). "It has been verified that a CALR alteration is closely associated with multiple immune checkpoints at a genomic level, which strongly implicates a possible co‐contribution to immune surveillance and evasion of pancreatic cancer." (PMID 32508042, 2020). "Previous studies revealed that CALR enhanced EGF-induced EMT in pancreatic cancer cells via Integrin/EGFR-ERK/MAPK signaling pathway and repressed E-cadherin expression via Snail (SNAI1)/Slug in Madin-Darby canine kidney cells or mouse embryonic stem cells." (PMID 35641480, 2022). "HSP47 confers chemoresistance on pancreatic cancer cells by interacting with calreticulin and IRE1α." (PMID 35928554, 2022). "It has been found that PDIA3 and CALR are highly co-expressed in micrometastasis pancreatic cancer cell lines PC-1 and Capan-2." (PMID 34910788, 2021). "In contrast to the immune checkpoints, the results revealed that CALR is highly expressed in pancreatic cancer in comparison to the normal control tissue." (PMID 32508042, 2020). "Together, this evidence strongly suggests that CALR had a crucial impact on the antitumor immune response in pancreatic cancer therapy." (PMID 32508042, 2020). "We used publicly available gene expression data on pancreatic cancer patients to study the importance of checkpoint ligands, and propose CALR as a more promising target for the treatment of pancreatic cancer." (PMID 32508042, 2020). "The general landscape of CALR and immune checkpoint alteration in pancreatic cancer was compactly visualized, including fusion, amplification, deep deletion, truncating, and missense mutations." (PMID 32508042, 2020). "Intriguingly, the genomic alteration of calreticulin, the key mediator of chemotherapy‐induced cancer immunogenic cell death, was found to couple with immune checkpoints in pancreatic cancer." (PMID 32508042, 2020). "Intriguingly, the genomic investigation revealed that CALR was actually involved in the alteration of immune checkpoints in pancreatic cancer." (PMID 32508042, 2020). "Our previous study showed that Calreticulin (CRT) promoted the development of pancreatic cancer (PC) through ERK/MAPK pathway." (PMID 29072694, 2017). "According to our results, immune checkpoint blockade therapy combined with radiotherapy and chemotherapy in CALR‐upregulated tumors might be a more appropriate therapeutic strategy for pancreatic cancer and provide patients with an extra survival benefit." (PMID 32508042, 2020). "Taken together, calreticulin‐based therapy may represent a more promising prospect for pancreatic cancer immunotherapy than immune checkpoint blockade therapy." (PMID 32508042, 2020). "Moreover, the overexpression of calreticulin is relevant to shorter survival in pancreatic cancer and esophageal cancer." (PMID 30974841, 2019). "However, whether CALR is also indicative of therapeutic efficacy in pancreatic cancer remains largely unknown." (PMID 32508042, 2020). "In the PAN02 pancreatic cancer model, HMC nanoparticles facilitate tumor cell internalization, triggering robust ROS bursts that promote apoptosis and ICD, evidenced by elevated calreticulin (CRT) exposure, ATP secretion, and reduced nuclear HMGB1 retention." (PMID 41451226, 2025).